CCL2 (C-C motif chemokine ligand 2)
Diseases named in the same sentence as CCL2 in open-access papers (continued):
Sharing a sentence is not in itself a finding about the gene and the disease.
steatosis (continued). "The chemokine MCP-1 (CCL2) also figures among the top-scoring analytes that can predict noncirrhotic NAFLD versus healthy; it is significantly increased in the “simple steatosis” group compared to the healthy controls." (PMID 38015590, 2023). "For instance, compared to Zeb1WT/ApoeKO mice, Zeb1∆M/ApoeKO mice had higher body weight, greater steatosis, higher WAT immune infiltration, higher serum levels of pro-inflammatory markers (IL1β, IL2, IL12, leptin, CCL2), higher cholesterol and LDL, and lower HDL and glucose tolerance." (PMID 38097578, 2023). "Inhibition of SYK could ameliorate the inflammation and steatosis of NAFLD by reducing the activation of macrophages and the production of CCl2, IL-6 and TNF-α." (PMID 34506234, 2021). "Additionally, the results of AH patients, NIAAA, and ALD mouse models have indicated that excessive alcohol consumption inhibits the ADRB2/SIRT1/PGC-1α/PPARα pathway, leading to elevated levels of oxidative stress and cytokines such as CCL2, CXCL8, and CXCL10, accompanied by hepatic steatosis." (PMID 39640486, 2024). "In our study, the average serum concentrations of CCL-2 decreased with disease severity, such that in patients diagnosed with steatosis, NASH, fibrosis (with or without NASH), and advanced fibrosis, average serum concentrations were 570, 464, 457, and 445 pg/mL, respectively." (PMID 23405244, 2013). "Besides, chemokines such as monocyte chemoattractant protein 1 (MCP-1)/CCL2, RANTES/CCL5, and other CXC chemokines have gained special importance in the progression of NAFL to NASH by regulating insulin resistance and steatosis via the inflammatory crosstalk between liver and adipose tissue." (PMID 33603757, 2020).
lupus (84 papers, 2006 to 2025). "Another protein associated with organ damage, CCL2, was already reported in kidney damage in lupus murine models and in SLE patients with irreversible renal damage." (PMID 29026368, 2017). "MSCs from MRL.Faslpr mice and lupus patients exhibited reduced B cell–suppressive activity both in vivo and in vitro because of a decreased production of CCL2 and its antagonistic variant compared to control MSCs25." (PMID 28117437, 2017). "In conclusion, it is imperative to investigate dendritic cells, CCL2, the blood-brain barrier, and relevant diagnostic techniques to comprehensively explore and understand the mechanisms of cognitive impairment induced by systemic lupus erythematosus." (PMID 39403387, 2024). "Interestingly, CCL2 has recently been implicated in driving basophil trafficking in systemic lupus erythematosus (SLE) and in severe allergic reactions." (PMID 31281316, 2019). "Furthermore, CTSS-overexpressing mice showed a marked increase in the production of IL-17, TNF-α, IFN-α and IFN-γ, which are known to be associated with lupus development, and the chemoattractants CCL2, CCL7 and CCLl12, which are activated by IFN-α to attract monocytes to inflammatory sites." (PMID 34381063, 2021). "Although MSCs suppress normal B-cell proliferation, differentiation, and antibody secretion, CCL2 silencing blocks the suppressive effects on B cells in the MSCs of systemic lupus erythematosus (SLE) patients." (PMID 36110206, 2022). "CCL2 has been shown to be one of three chemokines which elevated levels precede a period of lupus exacerbation, indicating that they would be good predictors of increased lupus activity." (PMID 35207538, 2022). "CCL1 and CCL2 promote basophil recruitment in skin lesions in patients with systemic lupus erythematosus." (PMID 36518763, 2022). "It is known from animal lupus models and from studies in patients with lupus nephritis that inflammatory chemokines, especially CCL2 and CCL5, were readily detectable in the kidney tissue and urine." (PMID 27852285, 2016). "By blocking the interaction between CCR2 and CCL2 in MRL/lpr lupus-prone mice, studies have shown that CCL2/CCR2 network contributes to LN development through both systemic and local mechanisms." (PMID 27403037, 2016). "Same as shown in lupus-prone mice, CCL2 is mainly expressed in the tubulointerstitial region of the kidney in SLE patients." (PMID 27403037, 2016). "The second most highly represented gene is CCL2, which links with four diseases: lupus, IBD, COPD, and dermatitis." (PMID 27089880, 2016). "Expression of mRNA for TNF-α, IL-1β, and CCL2 in kidney tissue was reduced in both strains of lupus-prone mice following treatment with ISO-1." (PMID 26617609, 2015). "Although both cytokines were argued to be elevated in the scenario of SLE, CCL2 was regarded as an important biomarker for lupus nephritis flair, and CXCL8 for lupus associated interstitial lung diseases." (PMID 25889297, 2015). "Fli-1′s role in lupus may be partly due to the production of pro-inflammatory mediators such as IL-6 and CCL2, which have been alleviated in endothelial cells and splenic T cells in Fli-1 heterozygous lupus mice." (PMID 40305194, 2025). "The secretion of CCL2 by dendritic cells induces pyroptosis in vascular endothelial cells, thereby promoting blood-brain barrier damage and triggering cognitive impairment in patients with systemic lupus erythematosus." (PMID 39403387, 2024). "For example, CCL2-deficient MSCs fail to establish long-lasting contact with T cells and no longer ameliorate lupus symptoms." (PMID 34215321, 2021). "CCL2 expression localizes prominently to glomerular podocytes in several human and experimental proteinuric kidney diseases, including diabetic, hypertensive, membranous, lupus, and crescentic nephropathy." (PMID 34369383, 2021). "In addition, CCL2 is mainly expressed in the tubulointerstitial regions of the kidney in lupus-prone mice." (PMID 27403037, 2016).
lupus (continued). "In a serologic proteome study by antibody microarray in SLE, CCL2 was identified as one of the twelve upregulated proteins; furthermore CCL2 was one of three chemokines that would precede lupus flare, indicating that they are good predictors of increased SLE activity." (PMID 24451065, 2014). "STAT1 may be an important driver of lupus pathogenesis with STAT1 serving as an expression enhancer of CCL2 and CXCL10 in patients with high levels of STAT1." (PMID 24451065, 2014). "CCL2 is an emerging novel target in systemic lupus erythematosus (SLE) and lupus nephritis, in which the CCL2/CCR2 axis mediates the infiltration of macrophages and T cells into the nephron in nephritis." (PMID 35702353, 2022). "The role of the chemokine CCL2 on the immunomodulatory capacity of MSCs on B cells was suggested since MSCs isolated from lupus-like mice and SLE patients have an impaired inhibition activity on B cells proliferation and differentiation." (PMID 27847522, 2016). "In line with this hypothesis, it has been reported that the expression of the CCL2 on MSCs derived from SLE patients or lupus-like mice is lower than that in healthy or wild-type MSCs and that CCL2 overexpression in MSCs derived from SLE patients restored their immunosuppressive function on B cells." (PMID 27847522, 2016). "The inhibitory effect of A20 on CCL2 has been observed in multiple diseases, such as vitiligo, systemic lupus erythematosus (SLE), and acute endoplasmic reticulum (ER) stress, and these studies all point to the fact that A20 downregulates CCL2 primarily by inhibiting the NF‐κB signaling pathway." (PMID 39853876, 2025). "Previous studies have shown that Fli-1 is a positive regulator of CCL2, CCL3, CCL4, CCL5, CXCL9, and CXCL10 in the kidneys of Fli-1 heterozygote knockout mice with lupus and CXCL5 in dermal small vessels from Fli-1 knockout mice." (PMID 40305194, 2025). "We found that expression of CCL2, CCL3, CCL4, CCL5, CCL8, CCL19, and CXCL10 increased 1.6–5.6-fold in the kidney of lupus-prone MRL.Faslpr mice with advancing age from 9 to 16 weeks." (PMID 37567910, 2023). "CCL2, CCL3, CCL5, CXCL10, and CXCL16 are increased in lupus nephritis patients and lupus-prone MRL.Faslpr mice." (PMID 37567910, 2023). "We also found that expression of CCL2, CCL3, CCL4, CCL5, CCL8, CCL19, and CXCL10 increased 1.6–5.6-fold in the kidney of lupus-prone MRL.Faslpr mice with advancing age from 9 to 16 weeks." (PMID 37567910, 2023). "The aim of this study was to investigate the correlation between IFN-α-induced chemokines CCL2, CXCL10 and CCL19 and disease activity in patients with systemic lupus erythematosus." (PMID 35207538, 2022). "We also found that deleting IL-22 or IL-22R downregulated CCL2 and CXCL10 expression, and decreased the filtration of macrophage into the kidney of lupus-prone mice." (PMID 33717066, 2021). "In human and murine lupus nephritic tissues, enhanced NF-κB activation was also detected, and this could drive the proliferation of mesangial cells (a primary lesion characteristics of lupus nephritis) and expression of a range of chemotactic factors, including CCL2, CCL5, MCP-1, and IL-8, in vitro." (PMID 31546763, 2019). "The chemokines CCL2, CCL3, CCL5, CXCL10, CXCL12, CXCL13, and CX3CL1 are expressed in the nephritic kidney of lupus-prone mice and SLE patients and increase inflammatory cell infiltration into the kidney." (PMID 30057623, 2018). "Two different combined inflammatory and lymphoid chemokine scores were investigated using CCL2, CXCL10 and CCL19 (score used successfully in lupus) and CXCL9, CXCL10, CXCL13 and CCL19 data." (PMID 24278364, 2013). "Here, we consider the genes CXCL11, CCL2 and APOBEC3A, as they are connected with autoimmune diseases, including systemic lupus erythematosus and thus potential therapeutic targets in the management of patients with lupus and, likely, other interferonopathies." (PMID 37770709, 2023).
lupus (continued). "For example, the serum levels of the IFN-α-induced chemokines CCL2, CXCL10 and CCL19 were found to correlate with lupus patient age and disease duration and thus have implications for monitoring disease activity and the determining the degree of organ damage in SLE." (PMID 37198402, 2023). "In addition, multiple chemokines, including CCL2, CCL5, and CXCL10, were expressed at higher levels in PVAT and plasma from lupus mice." (PMID 37006244, 2023). "Levels of chemokines CCL2, CXCL10 and CCL19 in lupus patients’ serum were measured by ELISA." (PMID 35207538, 2022). "By RNA-Seq, we found that gene expression of local chemokines in the kidney of lupus-prone mice was altered, and qRT-PCR further confirmed down-regulated expression of CXCL1, CCL2, and CXCL10 in the kidney of IL-22 or IL-22R KO MRL/lpr mice compared with MRL/lpr mice." (PMID 33717066, 2021). "Taken together, our imaging study demonstrates that CCL2 enables the prolonged MSC–T cell interactions needed for sufficient suppression of autoreactive T cells and helps to understand how MSCs ameliorate symptoms in lupus-prone MRL.Faslpr mice." (PMID 28117437, 2017). "Moreover, a transcription factor, Fli1, has been shown to directly bind the promoter region of CCL2 and CCL5 genes to promote their expression in primary endothelial cells of the kidney in NZM2410 lupus-prone mice." (PMID 27403037, 2016). "In lupus-prone mice, CCR2 and CCL2 are increased in the kidney during the development of LN, suggesting the recruitment of CCR2+ leukocytes into the inflamed kidney by CCL2." (PMID 27403037, 2016). "Further investigation reported that cerebral spinal fluids (CSF) MCP-1/CCL2 levels were significantly higher in neuropsychiatric syndromes of systemic lupus erythematosus (NPSLE) patients than those non-NPSLE patients." (PMID 22312407, 2012). "For example, secretion levels of CCL2, CCL3, CCL4, CCL5, CCL19, CXCL10, and CXCL12 are increased in the kidney of lupus-prone mice and SLE patients during the development of nephritis." (PMID 37567910, 2023). "The lack of CCL2 expression impaired MSCs’ suppression on B cells in lupus." (PMID 34215321, 2021). "Although microglia were reported to be important for the production of CCL2 during acute inflammation, the level of Ccl2 expression was not increased in FcγRIIB−/−Yaa mice in the present study, suggesting the polarizing status of microglia during lupus is different from that in acute inflammation." (PMID 31888754, 2019). "Mesangial cells from lupus-prone mice, compared to nonlupus mice, were more sensitive to lipopolysaccharide (LPS) stimulation as shown by the higher TLR4, MyD88, and NFκB expression and higher CCL2 production, suggesting a mechanism of how bacterial infections accelerate lupus disease." (PMID 27403037, 2016).
Cognitive impairment (82 papers, 2012 to 2026). Abnormal cognition is characterized by deficits in thinking, reasoning, or remembering. "MCP1/CCL2, which modulates leukocyte inflammatory responses, has been linked to disease severity in AD and mild cognitive impairment (MCI)." (PMID 40305176, 2025). "Cxcl13, Ccl2 and Ccl19 are 3 pro-inflammatory chemokines previously associated with cognitive impairments and that are also upregulated in AD, Ccl19 being a peripheral biomarker." (PMID 41216177, 2025). "The activation of microglia by CCL2 has also been reported in different pathological situations associated with neuroinflammation and cognitive impairment." (PMID 38139078, 2023). "Based on the results above, we could tentatively establish the following findings: the CCL2 gene plays a role in causing cognitive impairment in patients with NPSLE, and mature dendritic cells enhance CCL2 secretion via the RSAD2-ISG15 axis." (PMID 39403387, 2024). "Elevated CCL2 levels have been associated with brain atrophy and cognitive impairment." (PMID 39201480, 2024). "Therefore, in this study, we investigated the effect of naringin on CCL2-induced cognitive impairment and elucidated the possible underlying mechanisms." (PMID 32103758, 2020). "As such, we suspect that cognitive impairment is associated with CCL2 and that CCL2 may be an important pathogenic factor of HAND and other cognitive impairment diseases." (PMID 32185196, 2020). "Thus, as a potential proinflammatory mediator, we postulated that CCL2 is closely associated with neuroinflammation and cognitive impairment." (PMID 32103758, 2020). "Higher peripheral MCP-1 levels, also known as (C-C motif) ligand 2 (CCL2), have been associated with cognitive impairment or decline." (PMID 41153321, 2025). "The onset of Mild Cognitive Impairment (MCI), a state of cognitive decline between normal aging and dementia, is associated with CCL2 levels." (PMID 39011039, 2024). "In the context of neurological aging, elevated levels of CCL2 have also been observed in the brains of individuals with cognitive impairments and in animal models of neurodegenerative diseases such as AD." (PMID 39201480, 2024). "In patients with AD, there was a positive correlation between cognitive impairment and the CCL2 concentration in the CSF." (PMID 36551169, 2022). "A further study also showed that CSF CCL2 concentrations correlated with the extent of brain atrophy and cognitive impairment in AD, with one report suggesting that higher levels were associated with more rapid progression from MCI to AD." (PMID 34602080, 2021). "Meanwhile, it has been reported that CCL2 is not only overexpressed in the CSF of patients with HAND but is also overexpressed in the CSF of patients with cognitive impairment in Parkinson's disease." (PMID 32185196, 2020). "With this knowledge, we injected CCL2 into the bilateral hippocampi of rats to establish a cognitive disorder model as a potential mechanism for HAND." (PMID 32185196, 2020). "Taken together, these data imply that Tanshinone IIA can ameliorate CCL2-induced learning memory and cognitive impairment by impacting oxidative stress, inflammation, and apoptosis." (PMID 32185196, 2020). "Our present study used brain stereotactic technology to induce cognitive impairment in rats by injecting CCL2 (5 ng) into the bilateral hippocampus." (PMID 32185196, 2020). "Collectively, these results revealed the protective role of naringin against CCL2-induced cognitive impairment." (PMID 32103758, 2020). "Expression of IL1β and CCL2 is increased in AD, and both have been discussed as pathogenicity factors and biomarkers for, e.g., progression from mild cognitive impairment (MCI) to AD." (PMID 32878020, 2020). "These behavioral test results suggest that Tan IIA has a significant protective effect on CCL2-induced learning memory and cognitive impairment in rats." (PMID 32185196, 2020).